SNX3 (sorting nexin 3)
Description:
Phosphoinositide-binding protein required for multivesicular body formation. Specifically binds phosphatidylinositol 3-phosphate (PtdIns(P3)). Can also bind phosphatidylinositol 4-phosphate (PtdIns(P4)), phosphatidylinositol 5-phosphate (PtdIns(P5)) and phosphatidylinositol 3,5-biphosphate (PtdIns(3,5)P2) (By similarity). Plays a role in protein transport between cellular compartments. Together with RAB7A facilitates endosome membrane association of the retromer cargo-selective subcomplex (CSC/VPS). May in part act as component of the SNX3-retromer complex which mediates the retrograde endosome-to-TGN transport of WLS distinct from the SNX-BAR retromer pathway. Promotes stability and cell surface expression of epithelial sodium channel (ENAC) subunits SCNN1A and SCNN1G (By similarity). Not involved in EGFR degradation. Involved in the regulation of phagocytosis in dendritic cells possibly by regulating EEA1 recruitment to the nascent phagosomes. Involved in iron homeostasis through regulation of endocytic recycling of the transferrin receptor TFRC presumably by delivering the transferrin:transferrin receptor complex to recycling endosomes; the function may involve the CSC retromer subcomplex (By similarity). Involved in regulation of neurite outgrowth in primary neurons (By similarity). Required for trafficking of WLS to the early endosome for recycling which promotes both canonical and non-canonical WNT signaling and is essential for neural tube closure (By similarity). (Microbial infection) In the case of Salmonella enterica infection, plays a role in maturation of the Salmonella-containing vacuole (SCV) and promotes recruitment of LAMP1 to SCVs.
Synonyms: Grd19; MCOPS8; SDP3
Tractability: Small molecule: a structure with a bound ligand is known. PROTAC: UniProt records ubiquitination sites on it; ubiquitination databases record sites on it; its protein half-life has been measured.
Gene: Protein-coding gene on chromosome 6 (108,211,222 to 108,261,255, reverse strand). Ensembl gene ENSG00000112335.
Subcellular location: Early endosome; Cytoplasmic vesicle, phagosome
Pathways (Reactome):
Metabolism of proteins: Ub-specific processing proteases
Signal Transduction: WNT ligand biogenesis and trafficking
Gene Ontology:
Molecular function: phosphatidylinositol-3-phosphate binding; protein binding; protein phosphatase binding; retromer complex binding; phosphatidylinositol-3,5-bisphosphate binding; phosphatidylinositol-4-phosphate binding; phosphatidylinositol-5-phosphate binding; phosphatidylinositol binding; phosphatidylinositol phosphate binding
Biological process: host-mediated suppression of symbiont invasion; intralumenal vesicle formation; membrane invagination; negative regulation of early endosome to late endosome transport; negative regulation of phagocytosis; negative regulation of protein catabolic process; negative regulation of protein transport; protein to membrane docking; regulation of Wnt signaling pathway; response to bacterium; endocytic recycling; late endosome to Golgi transport; positive regulation of neuron projection development
Cellular component: clathrin-coated vesicle; cytoplasm; cytosol; early endosome; early endosome membrane; early phagosome; endosome membrane; extracellular exosome; retromer complex; phagocytic vesicle
Genetic constraint (gnomAD): Loss-of-function variants: 1 observed, 9.18 expected, observed/expected ratio (o/e) 0.11, 90% interval 0.038 to 0.52. That is too few expected variants to judge how well the gene tolerates losing a copy. Missense variants: 79 observed, 134.95 expected, observed/expected ratio (o/e) 0.59, 90% interval 0.49 to 0.71. Synonymous variants: 69 observed, 55.13 expected, observed/expected ratio (o/e) 1.25, 90% interval 1.03 to 1.53.
Homologues: Orthologues: chimpanzee SNX3 (100% identical), macaque SNX3 (100% identical), mouse Snx3 (100% identical), pig SNX3 (100% identical), tropical clawed frog snx3 (91% identical), zebrafish snx3 (88% identical), rabbit SNX3 (79% identical), Drosophila melanogaster Snx3 (71% identical), Caenorhabditis elegans snx-3 (67% identical), rat Snx3 (62% identical), guinea pig SNX3 (61% identical). Paralogues in human: SNX12 (78% identical), SNX2 (31% identical), SNX18 (30% identical), SNX4 (30% identical), SNX11 (29% identical), SNX30 (29% identical), SNX33 (28% identical), SNX1 (28% identical), SNX7 (28% identical), SNX10 (27% identical), SNX8 (26% identical), SNX9 (25% identical), and 3 more.
Diseases named in the same sentence as SNX3 in open-access papers:
SNX3 is named in the same sentence as 24 diseases in open-access papers, as found by Europe PMC text mining. Sharing a sentence is not in itself a finding about the gene and the disease. The quoted sentences say what the papers report.
osteosarcoma (4 papers, 2021 to 2024). A usually aggressive malignant bone-forming mesenchymal neoplasm, predominantly affecting adolescents and young adults. "In a related study, LINC01614 was significantly upregulated in osteosarcoma and could facilitate tumor progression through the miR-520a-3p/SNX3 axis." (PMID 36457749, 2022). "In osteosarcoma, LINC01614 accelerated SNX3 expression by binding miR-520a-3p, further leading to cancer progression." (PMID 38655053, 2024). "In osteosarcoma, LINC01614 as a ceRNA promoted tumor progression through the miR-520a-3p/SNX3 axis." (PMID 38655053, 2024). "Through the miR-520a-3p/SNX3 axis, LINC01614 accelerates the progression of osteosarcoma." (PMID 36843602, 2023).
cardiac failure (2 papers, 2025 to 2026). "Sorting nexin 3 (SNX3), belonging to SNXs family, is identified by our laboratory as a novel therapeutic target for heart failure." (PMID 41540011, 2026).
Sepsis (2 papers, 2023 to 2025). Sepsis is defined as life-threatening organ dysfunction caused by a dysregulated host response to infection. "Using this model, we identified five key genes for constructing the sepsis diagnostic model: SHKBP1, ICAM2, CTSD, SNX3, and SLC22A4." (PMID 41445732, 2025). "We established a diagnostic model based on five key genes(SHKBP1,ICAM2,CTSD,SNX3, and SLC22A4), and Kaplan-Meier survival analysis revealed that SHKBP1 was significantly correlated with both the diagnosis and prognosis of sepsis." (PMID 41445732, 2025). "Nevertheless, other hub genes such as ICAM1, CTSD, SNX3, and SLC22A4 also demonstrated biological relevance in sepsis and may contribute to disease pathogenesis through complementary mechanisms." (PMID 41445732, 2025).
colorectal cancer (1 paper, 2023). A primary or metastatic malignant neoplasm that affects the colon or rectum. "Through the β-linked protein pathway, SNX3 prevents the migration and invasion of colorectal cancer cells by reversing the epithelial-to-mesenchymal transition." (PMID 36843602, 2023).
fibrosis (1 paper, 2026). the formation of excess fibrous connective tissue in an organ or tissue in a reparative or reactive process. "The SNX3 protein level was negatively correlated with pulmonary function and positively correlated with fibrosis area." (PMID 41540011, 2026). "Compared to BLM-induced CTL mice, Snx3-cKO mice had significantly improved pulmonary appearance, fibrosis areas, collagen fibrils, elastic fibers, hydroxyproline concentration and lung dysfunction." (PMID 41540011, 2026). "The levels of β-catenin protein, pulmonary dysfunction, fibrosis areas, collagen fibrils, and hydroxyproline concentration were significantly reduced in Snx3-cKO mice compared with BLM mice, but AAV6-CK-1α reversed this lung-protective effect of SNX3 deficiency, as was also observed in AT2 cells." (PMID 41540011, 2026).
liver fibrosis (1 paper, 2026). "In addition, SNX3-driven activation of Wnt/β-catenin may also cause extensive organ fibrosis, such as cardiac fibrosis and liver fibrosis, which needs to be confirmed by further research." (PMID 41540011, 2026).
lung carcinoma (1 paper, 2018). "Lung cancer cells exhibit hyperphosphorylation of the corresponding serine in SNX1, SNX2, SNX3, and SNX2136,39." (PMID 29520003, 2018).
lung disease (1 paper, 2026). "In this study, we illustrate that SNX3 was elevated in lung tissues from patients with lung disease and in a mouse model of bleomycin (BLM) -induced PF." (PMID 41540011, 2026). "The expression of Snx3 was increased in lung disease tissues compared with healthy controls." (PMID 41540011, 2026).
pulmonary fibrosis (1 paper, 2026). Chronic progressive interstitial lung disorder characterized by the replacement of the lung tissue by connective tissue, leading to progressive dyspnea, respiratory failure, or right heart failure. "Pulmonary fibrosis areas, deposition of collagen fibers, hydroxyproline concentration and increased fibrosis biomarkers were observed in Snx3-cTg mice." (PMID 41540011, 2026). "The SNX3 protein level was positively correlated with pulmonary fibrosis." (PMID 41540011, 2026). "Whether SNX3 has other key proteins involved in this pathway besides Wls to induce pulmonary fibrosis?" (PMID 41540011, 2026). "To this end, we screened inhibitors targeting SNX3 and identified a novel small molecule LC4, which effectively ameliorated pulmonary dysfunction and reversed pulmonary fibrosis." (PMID 41540011, 2026). "Furthermore, we screened inhibitors targeting SNX3 and identified a novel small molecule, LC4, which effectively ameliorated pulmonary dysfunction and reversed pulmonary fibrosis." (PMID 41540011, 2026).
Salmonella Infections (1 paper, 2017). Infections with bacteria of the genus SALMONELLA. "Previous studies have suggested that SNX3 is a component of a tubular endosomal network induced by Salmonella infection and is involved in the maturation of Salmonella-containing vacuoles." (PMID 28903313, 2017).
cancer (8 papers, 2021 to 2025). A tumor composed of atypical neoplastic, often pleomorphic cells that invade other tissues. "Disruptions in SNX3 function have been linked to a range of diseases, including neurodegenerative disorders 54, cardiovascular conditions 13, and cancer 50, highlighting its significance in upholding cellular equilibrium." (PMID 39006843, 2024). "Many previous studies have shown that SNX3 has a function in malignant tumors." (PMID 36843602, 2023). "Recently, SNX3 was also shown to bind with EGFR using biotin proximal labelling approach, and SNX5 immunoprecipitated with EGFR in Huh7—a hepatocyte-derived carcinoma cell line." (PMID 36359754, 2022). "Moreover, phosphorylation at corresponding sites in SNX1, SNX3, SNX12, and SNX17 has been reported in various cancer types, hinting at a potential link between SNX phosphorylation and disease states." (PMID 40349777, 2025).
tumor (4 papers, 2022 to 2024). "To investigate the role of SNX3 in tumor progression in vitro, we constructed stable cell lines with SNX3 over-expression by lentiviral infection." (PMID 39310106, 2024). "In contrast, SNX3 and LGALS2 are antitumor factors that inhibit tumor cell growth and metastasis, which is consistent with the phenotype of type I conventional DCs." (PMID 37533434, 2023). "Furthermore, we performed immunohistochemistry analysis and confirmed the high expression of SNX3 in saline and cetuximab groups, along with low expression of p62, when compared to honokiol and honokiol + cetuximab groups in orthotopic KRASG13D mutant tumor sections." (PMID 39310106, 2024).
infection (3 papers, 2015 to 2025). The state of being infected such as from the introduction of a foreign agent such as serum, vaccine, antigenic substance or organism. "The same pattern of SNX3 distribution was also observed in Balb3T3 cells, which provide better resolution for spatial analysis in the later stages of infection." (PMID 40299528, 2025). "In MCMV-infected cells, SNX3-decorated EEs are relocated to the pericentriolar region during the E phase of infection, consistent with their accumulation and expansion within the pre-AC." (PMID 40299528, 2025). "In the E phase of infection (6 and 16 hpi), the SNX3-positive structures concentrated in the perinuclear region, and unlinked Golgi cisternae expanded into a ring-like structure, forming the basic configuration of the pre-AC." (PMID 40299528, 2025). "The inhibition of HIV-1 fusion and infection in cells depleted of Rab5A, SNX3 or SNX10 suggests that this virus enters CEM.CCR5 cells via an endocytic pathway." (PMID 30691001, 2019). "In this context, it is interesting to note that Salmonella enterica serovar Typhimurium acquire SNX1 and SNX3, and SNX1 is found on spacious vacuole-associated tubules early in the infection process." (PMID 26042774, 2015). "To test whether SNX3 depletion affects virion assembly and egress, we analyzed the intracellular distribution of fluorescent capsids after infection of cells with mCherry-SCP-MCMV." (PMID 40299528, 2025). "At the end of the E phase of infection, at 16 hpi, SNX27 and SNX3 were concentrated at the same vacuolar structure and likely at the same membrane domains, as colocalization was significantly higher than at the beginning of infection." (PMID 40299528, 2025). "Therefore, the aim of this study was to investigate whether the SNX3-dependent pathway contributes to the expansion of Rab10-PD, pre-AC biogenesis, and infectious virion production during infection with MCMV." (PMID 40299528, 2025). "Therefore, we first investigated whether SNX3 accumulates in the pre-AC during the E phase of infection, which includes the dislocated Golgi and expanded EE-RE/ERC-TGN membranes, and in the fully established perinuclear megastructure of AC after viral DNA replication and MCMV L gene expression." (PMID 40299528, 2025). "To analyze this, we performed a Western blot analysis of SNX3 protein expression during the relevant phases of the MCMV replication cycle and found that SNX3 expression was upregulated in the E phase of infection and persisted in the L phase." (PMID 40299528, 2025). "As infection progressed and the pre-AC matured into the AC, the colocalization of SNX27 with SNX3 further increased, suggesting that the area for recycling CIE cargo within the AC is continuously expanding." (PMID 40299528, 2025). "We next asked if depletion of Rab5A, SNX3 or SNX10 in CEM.CCR5 cells inhibits HIV-1 fusion and infection by modulating the virus uptake." (PMID 30691001, 2019). "The requirement for Rab5A, SNX3 and SNX10 for efficient HIV-1 fusion and infection in CEM.CCR5 cells suggests that endocytosis plays a role in productive entry into these cells." (PMID 30691001, 2019). "The expansion is associated with the increase in SNX3-162 expression, which is unrelated to the increase in transcriptional activity, as the SNX3 transcript was not altered during the E phase of infection." (PMID 40299528, 2025). "In the L phase of infection, at 48 hpi, the AC was fully established and consisted of expanded Golgi cisternae loaded with the MCMV glycoprotein gpM55 surrounding concentrated SNX3-positive structures, and SNX3-positive structures were reduced at the cell periphery." (PMID 40299528, 2025).
bacterial infection (1 paper, 2017). "Although some SNX family proteins, such as SNX3 and SNX5, have been shown to affect phagocytosis, our results suggested that SNX10 deficiency did not affect the phagocytosis of macrophages following bacterial infection." (PMID 28903313, 2017).
heart diseases (1 paper, 2026). "For example, our laboratory reported that SNX3 induces heart diseases by reversing the transport of its cargo proteins to the PM or nucleus." (PMID 41540011, 2026).
SNX3 also shares sentences with these, for which no sentence is quoted: microcephaly (2 papers); breast carcinoma (1); chlamydial infection (1); dementia (1); glioma (1); Kawasaki disease (1); microphthalmia (1); neuroblastoma (1); prostate carcinoma (1).